INS (insulin)
Diseases named in the same sentence as INS in open-access papers (continued):
Sharing a sentence is not in itself a finding about the gene and the disease.
Hyperglycemia (continued). "Although hyperglycemia is commonly interpreted as a negative prognostic indicator, its association in acute settings may be more linked to reduced insulin sensitivity from acute pathologies rather than glucose administration itself." (PMID 38892539, 2024). "Moreover, we assessed in diabetic mice the effect of HK M. aurum on the expression of key proteins involved in glucose transport and metabolism in the liver and skeletal muscle which are insulin-sensitive tissues significantly influenced by insulin insufficiency and hyperglycemia." (PMID 39377070, 2024). "Previous studies have hypothesised that TG might play a role in compensatory hyperinsulinemia, and that a lack of TG could cause a decrease in insulin compensation for hyperglycaemia." (PMID 39296580, 2024). "Consequently, insulin fails to facilitate glucose uptake, causing hyperglycemia and hyperinsulinemia, prompting increased insulin secretion by pancreatic β-cells to regulate glucose levels." (PMID 38441531, 2024). "A review summarizing studies in animals as well as a few in humans describes that hyperglycemia-induced aberrant levels of INS or INS growth factors (IGF) may lead to neuropathic complications, intensifying pain through mechanisms such as central sensitization." (PMID 39595105, 2024). "Thus, imeglimin may improve hyperglycemia by enhancing insulin secretion and preserving β-cell mass, likely via the maintenance of mQC in pancreatic β-cells." (PMID 38485716, 2024). "Furthermore, hyperglycemia creates a sublethal level of ER stress, which increases insulin secretion via IRE-1α and pancreatic β-cell proliferation via ATF6, while sustained stimulation of all three UPR pathways by saturated FFAs culminates in pancreatic β-cell apoptosis." (PMID 39063184, 2024). "Glucocorticoids may precipitate acute and sustained hyperglycaemia by countering insulin action." (PMID 38907161, 2024). "Hence, we speculate that hyperglycemia in BI-1–/– mice may be primarily due to an ER stress-dependent dysfunction of the endocrine pancreas to secrete adequate amounts of insulin at an early age or under diet-induced diabetic conditions." (PMID 38744890, 2024). "It was reported that XAB2 may exert as a regulator in hyperglycemia with chronic insulin." (PMID 39777224, 2024). "Hence, EtOH-WCg may increase insulin sensitivity because less insulin is required to ameliorate hyperglycemia." (PMID 39478960, 2024). "Thus, combining intensive insulin therapy with CGM to fight stress hyperglycemia in the 3rd ACR tertile group in clinical daily practice could presumably have a direct effect on the patient’s prognosis in the short-term after AIS diagnosis." (PMID 38890732, 2024). "Additionally, the review elucidates the function of the placenta and placental hormones in fetal development, as well as the impact of hyperglycemia, insulin resistance and adipokines on fetal and neonatal nutritional programming and predisposition to metabolic complications in adulthood." (PMID 39683486, 2024). "This suggests that NLaz knockdown may enhance the sensitivity of cells to insulin when Bursicon signaling is diminished, potentially explaining the reversal of hyperglycemia, since enhanced insulin signaling facilitates increased cellular glucose uptake from circulation." (PMID 39033139, 2024). "Consequently we investigated whether pharmacological GCGR agonism in a diet-induced obese model of chronic hyperglycaemia can alleviate the deleterious effects of high-fat diet on co-ordinated insulin secretion." (PMID 38677509, 2024). "Hyperglycemia-induced seizures tend to be refractory to anti-epileptic medications, and some anti-epileptic drugs like phenytoin may exacerbate and worsen seizures as they inhibit insulin secretions." (PMID 39077240, 2024).
Hyperglycemia (continued). "Interestingly, the stimulation of pancreatic islets with very high concentrations of TNF, IFNγ and IL-1β inhibited insulin secretion, indicating that during severe, life-threatening infection these cytokines are involved in facilitating stress-induced hyperglycemia." (PMID 39107476, 2024). "Moreover, animal experiments have shown that artificial sweeteners may impair secretion of insulin by lowing release of glucagon-like peptide-1, resulting in hyperglycemia." (PMID 39085903, 2024). "Thus, any vascular effects from hyperglycemia could potentially be influenced by increased insulin concentrations." (PMID 39342285, 2024). "In addition, the persistent hyperglycemia leads to destruction of functional insulin-producing β-cells, immunostaining analysis of the harvested pancreas tissue showed that the percentage of insulin-positive area was profoundly decreased in db/db mice compared with control mice." (PMID 38532899, 2024). "In HHS, compared with DKA, there is less severe insulin deficiency and, therefore, sufficient insulin to prevent ketogenesis but not enough to prevent hyperglycaemia, due to increased hepatic glucose production and decreased glucose utilisation by peripheral tissues." (PMID 38907161, 2024). "This challenge is underscored by contrasting results across animal studies, where some medications, such as insulin, show promise in controlling blood glucose and promoting bone healing, while others, like sitagliptin, fail to overcome the detrimental effects of sustained hyperglycemia." (PMID 39723258, 2024). "Low GR foods may have an important role to play in the prevention and control of those at risk of developing T2DM, and they have been shown to significantly reduce the frequency of hyperglycemia, decrease total cholesterol and improve insulin sensitivity and postprandial insulin response (IR)." (PMID 38892603, 2024). "Insulin or insulin secretagogues (e.g. sulfonylurea) may inhibit the anti-tumor activity of PI3K inhibitors, and thus treatment of PI3K inhibitor-associated hyperglycemia should prefer alternative approaches such as a low carbohydrate diet, metformin, SGLT2i, or dose reduction of the PI3K inhibitor." (PMID 39437820, 2024). "This hyperglycemia is caused by a lack of insulin secretion or sensitivity to insulin." (PMID 38380214, 2024). "Besides the trophic effect of insulin on the acinar component, it is possible that another potential mechanism that links endocrine and exocrine insufficiency is based on a direct toxic effect of hyperglycemia." (PMID 38398492, 2024). "However, steroids can induce hyperglycaemia by altering beta cell function and insulin sensitivity." (PMID 38644759, 2024). "Hyperglycemia and elevated insulin levels could explain this phenomenon." (PMID 39200168, 2024). "Therefore, insulin insensitivity or elevated glucagon can be ruled out as a cause of hyperglycaemia upon B7-H4 knockout in β cells." (PMID 39571901, 2024). "Thus, INS-DF appears to lead to a suppression of glucose-induced GC that could then contribute to hyperglycemia by increasing EGP." (PMID 38265288, 2024). "Moreover, the insulin response to oGTT was severely blunted at this age, though fasting insulin remained relatively high in response to sustained hyperglycemia, which is indicative of 1) insufficient β-cell insulin secretion and 2) insulin resistance at the level of the receptor, respectively." (PMID 37899754, 2024). "Without insulin, glucose accumulates in the bloodstream, causing hyperglycemia." (PMID 39310514, 2024). "The mesenchymal stromal cells with the insulin-secreting property isolated from the adipose tissue conjointly with the hematopoietic stem cells extracted from bone marrow, co-infused into the thymic portal circulation and subcutaneous tissue were found to regulate the hyperglycemia in TIDM patients." (PMID 38255714, 2024).
Hyperglycemia (continued). "Furthermore, the incidence of grade 3 or higher hyperglycaemia, defined as the initiation of insulin therapy according to the Common Terminology Criteria for Adverse Events (CTCAE) version 5.0, was lower in imatinib-treated patients (11% vs. 20%, Chi-squared test p = 0.022)." (PMID 38424569, 2024). "Due to the β-cell-intrinsic role of TALK-1 L114P channels, the effect of somatostatin on glucose-stimulated insulin secretion might be limited; however, it remains to be determined if the fasting hyperglycemia observed in KCNK16-MODY patients is due in part to elevated glucagon secretion." (PMID 38700926, 2024). "There are reports of adults with T1DM that omit or restrict the insulin dose to lose or to control the body weight, which may lead to a poor metabolic control and can favor the development of short- and long-term complications resulting from hyperglycemia." (PMID 38892513, 2024). "Likewise, the number of overnight glycemic alterations and span of interrupted sleep in the same night are other influencing factors: “Those nights [experiencing hyperglycemia] I've to wake up five or six times to go to the bathroom, even if I've had my insulin dose and levels are getting low." (PMID 39022652, 2024). "This decrease in insulin mRNA could be due to toxicity of beta cells in the face of hyperglycemia." (PMID 39684905, 2024). "To challenge this idea, we first examined whether the treatment with SCH23390 and quinpirole mitigated hyperglycemia, hyperinsulinemia, and hyperprolactinemia in Trappc9-KO mice, as dopamine transmission modulates glucose homeostasis and inhibits prolactin and insulin secretion." (PMID 38889014, 2024). "Finally, in patients with enteral or parenteral nutrition to correct or prevent hyperglycemia, the use of subcutaneous rapid-acting insulin every 4 or 6 hours could be considered." (PMID 38559691, 2024). "Alternative routes of insulin delivery, including intraperitoneal and inhaled insulin, are being investigated and the more rapid absorption compared to the subcutaneous route may counteract postprandial hyperglycemia and minimize hypoglycemia." (PMID 39390689, 2024). "Given that the LHb has also been observed to play a role in metabolic response to insulin and to determine whether the observed effects of hyperglycemia were specific to the vMHb, which contains presumably vulnerable cholinergic neurons, we also examined mitochondria in the adjacent LHb." (PMID 39763617, 2024). "Therefore, compounds from Siraitia grosvenorii have several targets by which they may ameliorate hyperglycemia (i.e., SG-gly, maltase inhibitory activity; SG-ex, anti-oxidative activity in the pancreas; mogrol, insulin secretory activity)." (PMID 38332164, 2024). "In vitro, low-dose GSK2606414 treatment increased glucose-stimulated insulin secretion (GSIS) levels and pancreatic islet insulin content in mouse and human islets, while in vivo treatment with GSK2656157 enhanced GSIS and alleviated hyperglycemia in an insulin-deficient mouse model." (PMID 38509524, 2024). "DM is defined as a chronic disease, characterized by hyperglycemia with disturbances of carbohydrate, fat, and protein metabolism resulting from either a defect in insulin secretion by the pancreas or impairment in insulin action in insulin-sensitive tissues, or both." (PMID 39337311, 2024). "Altogether, these findings could indicate that beta cells of HFD+TAC animals are in a compensatory stage with a reduced proliferative capacity in which transcriptional factors related to insulin production and beta cells hypertrophy are overexpressed to cope with the status of hyperglycaemia and IR." (PMID 38745946, 2024). "However, prolonged hyperglycemia and impaired insulin signaling may block autophagic flow, leading to the accumulation of faulty cellular parts, contributing to β-cell dysfunction." (PMID 39407941, 2024).
Hyperglycemia (continued). "Furthermore, whilst in intensive care units, some donors may be given insulin in response to donor hyperglycaemia of varying aetiologies." (PMID 38832357, 2024). "Therefore, impaired insulin signalling along with hyperglycaemia may induce tau phosphorylation and subsequent cleavage, contributing to the increased risk of AD in diabetic patients." (PMID 36372924, 2023). "The lower risk of nocturnal hypoglycaemia in the participants could be linked to a ratio of prandial/basal insulin, residual beta cell function and insulin secretion, the more pronounced tendency to hyperglycaemia in premix patients and behavioural modification." (PMID 36882852, 2023). "Additionally, it improves insulin sensitivity in placental cells during hyperglycemia." (PMID 37669960, 2023). "Furthermore, pancreatic injuries might also lead to insulin level disruptions, resulting in hyperglycaemia." (PMID 38053350, 2023). "When subcutaneous insulin is utilized to treat intraoperative hyperglycemia, particular attention needs to be paid to factors that increase insulin sensitivity and resistance, to ensure that insulin is dosed appropriately, to prevent swings of hypo and hyperglycemia." (PMID 37120562, 2023). "Moreover, hyperglycemia-induced elevation of insulin might increase the activity of the sympathoadrenal system, which is known for its cancer-stimulating effect." (PMID 36829437, 2023). "Moreover, long-term hyperglycemia can promote brain insulin resistance, which may in turn promote Aβ aggregate accumulation and tau hyperphosphorylation." (PMID 37373216, 2023). "Inadequate insulin production and impaired muscle glucose uptake result in significantly critical complications such as nephropathy, retinopathy, and neuropathy, as well as the production of superoxide free radicals due to hyperglycaemia-induced protein glycation." (PMID 37133312, 2023). "Additionally, it may upregulate gluconeogenesis pathways and suppress glycolysis pathways and insulin signaling in peripheral tissues, resulting in hyperglycemia and IR." (PMID 37512897, 2023). "Also, the in vivo studies of the ethyl acetate fraction of the ethanol crude extract in diabetic rats indicated the ability of T. grandis to improve pancreatic histology, insulin secretion, and sensitivity, thus reducing postprandial hyperglycaemia within the safety used at a dose of 300 mg/kg.bw." (PMID 38203195, 2023). "Furthermore, in order to prevent decreasing health status confounding behavioral readouts, STZ rats with confirmed hyperglycemia were treated with insulin every other day, and pharmacological experiments were performed 21 days post-STZ treatment as recommended." (PMID 36830733, 2023). "The pathogenesis of GDM in pregnant women primarily involves insulin resistance and β-cell defects, characterized by the inability of pancreatic β-cells to adequately respond to the increased insulin demands of pregnancy, contributing to varying degrees of hyperglycemia." (PMID 37900122, 2023). "Poor insulin administration might also exacerbate hyperglycemia and emergency visits." (PMID 36833075, 2023). "Although numerous clinical studies performed in healthy humans have established that acute hyperglycemia, sustained by mixed meals or oral glucose, could reduce arterial vascular function; however, diet influences autonomic production, insulin secretion, incretin secretion, and blood pressure." (PMID 36984870, 2023). "This usually results in low or no insulin, causing hyperglycemia." (PMID 38033739, 2023). "The same may be true of using large doses of insulin to correct hyperglycemia in sepsis." (PMID 37550630, 2023). "In addition to insulin, glucose may also be closely related to skeletal muscle maintenance, and hyperglycemia could inhibit muscle regeneration and accelerate sarcopenia." (PMID 37265691, 2023). "Besides hyperglycemia, impaired insulin production can induce several metabolic alterations." (PMID 38055691, 2023).
Hyperglycemia (continued). "Edible mushrooms have been studied for their potential to reduce hyperglycemia by looking into their antioxidant defenses, carbohydrate metabolism pathways, α-glucosidase and aldose reductase inhibitory activities, β-cell enhancement, and insulin-releasing activity." (PMID 36985818, 2023). "Hyperglycemia frequently occurs after breakfast in some diabetic patients, this so-called “dawn phenomenon” suggests that disruptions in the circadian clock may also disrupt the circadian rhythm of insulin sensitivity." (PMID 36891383, 2023). "In addition, WP as a fast digestible protein and a remarkable source of BCAAs promotes the circulation and release of insulin that may reduce postprandial hyperglycemia." (PMID 37798798, 2023). "However, in T2DM patients, incretin accounts for just 20% of total insulin secretion due to decreased incretin secretion and dysfunctional receptor or postreceptor signaling, resulting in a decreased postprandial insulin and C-peptide secretion response, which contributes to hyperglycemia." (PMID 37096236, 2023). "Analysis grouped risk loci into five major categories: insulin sensitivity/resistance, insulin secretion and fasting hyperglycemia, insulin processing defects, insulin secretion without change in fasting glucose levels, and no defined associations to glycemic traits." (PMID 37239940, 2023). "Accounting for glucose variation across the menstrual cycle is also imperative for individuals with conditions like type 1 diabetes, as increased glucose levels during the luteal phase may lead to hyperglycemia in diabetic individuals and should be considered when planning insulin therapy." (PMID 37567949, 2023). "Thus, it has been established that the most important factors for the development of AD are prolonged hyperglycemia, decreased insulin sensitivity, increased inflammatory processes, including the development of neuroinflammation, and lipotoxicity, which are typical for patients with T2DM." (PMID 36834685, 2023). "First, considering the maintenance of the model, we administered insulin intervention to some pigs with hyperglycaemia during follow-up, which may make our results somewhat different from the changes in cardiac structure and function under sufficient hyperglycaemia exposure." (PMID 36627647, 2023). "Intravenous insulin therapy is recommended to avoid blood glucose level above 150 mg.dl− 1 (8.2 mmol.l− 1) and below 100 mg.dl− 1 (5.5 mmol.l− 1) after cardiac surgery since intra and postoperative hyperglycemia was reported to increase postoperative morbidity and mortality." (PMID 37620974, 2023). "Notably, BG trajectories only start to diverge substantially after the post-PA meal as insulin sensitivity remains elevated for several hours during recovery, and further measures to avoid post-PA hyperglycemia might be required." (PMID 36791144, 2023). "Finally, n-3 PUFAs can increase insulin sensitivity and prevent hyperglycemia." (PMID 36832799, 2023). "Indeed, studies examining the timing and relationship between changes in beta cell molecular architecture, insulin secretion, insulin sensitivity and beta cell functional defects have identified the latter as the primary requisite for the development of hyperglycaemia." (PMID 36280617, 2023). "Thus, the cytokine storm in COVID-19 may exacerbate stress hyperglycemia as acute inflammation may further worsen insulin resistance." (PMID 37515156, 2023). "Effects of hyperglycemia, including excessive glucose influx to insulin-independent cells, may induce oxidative stress and secondary innate immunity dependent inflammatory response, which can damage cells within the CNS, thus promoting neurodegeneration and dementia." (PMID 37373216, 2023). "However, these groups presented fasting hyperglycemia and impaired insulin tolerance, which might have been due to enhanced gluconeogenesis fueled by propionate production caused by compositional changes in gut microbiota." (PMID 37242202, 2023).